FGF1 (fibroblast growth factor 1)
Diseases named in the same sentence as FGF1 in open-access papers (continued):
Sharing a sentence is not in itself a finding about the gene and the disease.
breast cancer (continued). "FGF1-Integrin-αVβ3-FGFR1 crosstalk has been shown to promote angiogenesis and tumorigenesis, and later shown to enhance EMT in breast cancer cell lines." (PMID 34068954, 2021). "Various studies measure the expression level of the FGF1 and FGFR1 in different cancers, including breast carcinoma, hepatocellular carcinoma and esophagus cancer." (PMID 34552869, 2021). "We utilised MCF-7 breast cancer cells transfected with either of two of the major VEGF isoforms, VEGF121 or VEGF165, or fibroblast growth factor-1 (FGF-1) to distinguish the effects of these factors on tumour growth, vascular function, and oxygen delivery." (PMID 14735189, 2004). "Ang1 was then overexpressed in a human breast cancer cell line (MCF-7) on its own and in conjunction with FGF1, an angiogenic factor shown to be able to increase the tumorigenicity of MCF-7 cells." (PMID 11027428, 2000). "For example, the artificially synthesized peptide AP8, designed using this approach and capable of specifically binding to FGF1, can block the activation of the ERK1/2 and AKT signaling pathways in breast cancer cells and vascular endothelial cells induced by FGF1." (PMID 41155018, 2025). "The subsequent step involved evaluating whether BIRC5, FGF1, RASSF6, SERPINE1 and STK4 could serve as targets for miRNAs differentiating breast cancer from the control." (PMID 41153630, 2025). "In endocrine-sensitive but not endocrine-resistant breast cancer cells, mitochondrial metabolism was also regulated by FGF1." (PMID 37608351, 2023). "In this study, we analyze how FGF1, compared to EGF, affects the survival of the MCF-7 model cell line, extensively applied in breast cancer research and treated with taltobulin, a cytotoxin belonging to the widely used group of drugs that inhibit tubulin polymerization." (PMID 37509496, 2023). "FGFR4, which can mediate signaling from FGF1, FGF4, and FGF8 subfamilies, may facilitate acquired and de novo resistance to endocrine therapies in breast cancer." (PMID 37800138, 2023). "In summary, FGF1, EGF and their receptors are important players in breast cancer development." (PMID 37509496, 2023). "Both FGF1 and FGF2 play a crucial role in breast cancer angiogenesis." (PMID 35193394, 2022). "On the contrary, FGF9 is highly expressed in breast cancer compared with normal tissue, although its expression is not as high as the expression of other FGFs like FGF1." (PMID 35193394, 2022). "The mitogenic growth factors FGF1 and FGF2, known to possess potent angiogenic properties, were increased in patients with malignant breast tumours and decreased in patients with benign breast lesions indicating their possible role in malignant cell transformation." (PMID 34997107, 2022). "In addition, breast cancer patients with high expression of ATAT1 and MAPK8, RASSF1, BCL2, CXCL8, and FGF1, had a poor prognosis." (PMID 34199510, 2021). "As the upstream of FGF1/HGF signaling pathway, CUX1 has been reported to contribute to the progression of luminal and basal breast cancer, help distinguishing Her2 subtype of breast cancer." (PMID 31480430, 2019). "The present study demonstrated that TGF-β1 markedly induced integrin αvβ3 expression, and blocking integrin αvβ3 by RNAi abrogated FGF1- and TGF-β1-induced wound healing in MCF10A cells as well as in a breast cancer cell line that naturally expresses moderate level of integrin αvβ3." (PMID 26334633, 2015). "Ligands that bind to ErbB receptors were the most broadly active (every tested ErbB ligand elicited a significant response in at least 35 lines), followed by FGF-1/2, HGF, and IGF-1/2, consistent with the known importance of these ligands in breast cancer biology." (PMID 24655548, 2014). "A total of 116 breast cancers and 37 biopsies taken from non-malignant breast were compared for FGF-1 mRNA expression using reverse transcriptase-polymerase chain reaction (RT-PCR) and significantly lower levels were found in the cancer tissues (P < 0.001)." (PMID 8519654, 1995).
breast cancer (continued). "The decreased levels of FGF-1 in breast cancer may indicate that stimulation of cancer cells is resulting in down-regulation of FGF-1 expression or may implicate FGF-1 as a differentiation factor rather than a growth factor at its physiological concentration in the breast." (PMID 8519654, 1995). "BIRC5, FGF1 and RASSF6 are unlikely to be targets of miRNAs significantly altered across five breast cancer subtypes in this study." (PMID 41153630, 2025). "FGF2, but not FGF1, was shown to enhance cisplatin toxicity in MCF-7 breast cancer cells and A2780 ovarian cancer cells, but not in SKOV3 ovarian cancer cells or a panel of pancreatic cancer cell lines." (PMID 34830951, 2021). "We have measured the amount of fibroblast growth factor 1 (FGF-1) mRNA and protein in primary breast cancers and non-malignant breast tissue and have found greatly reduced levels in breast cancer compared with non-malignant tissue." (PMID 8519654, 1995).
diabetes (52 papers, 2011 to 2026). "Although FGF1 has antidiabetic effects, the tumorigenic risks associated with chronic FGF1 administration have raised concerns about its use as a pharmacotherapy for diabetes." (PMID 40243151, 2025). "For instance, FGF-1 can reduce inflammation caused by diabetes, lower oxidative stress, resist cell apoptosis, and enhance cellular autophagy." (PMID 38542166, 2024). "FGF1, which encodes fibroblast growth factor 1, plays a vital role in embryonic development, wound healing, neurogenesis, angiogenesis, and the control of type 2 diabetes mellitus." (PMID 36836780, 2023). "In another study, central FGF1 injection delayed the onset of progressive beta cell loss in a rat model of diabetes." (PMID 37284218, 2023). "We found that treatment with a FGF1 variant (FGF1∆HBS) with reduced proliferative potency prevented diabetes-induced cardiac injury and remodeling and restored cardiac function." (PMID 33762571, 2021). "Taken together, our and the others’ studies suggest that the chronic inflammatory control is the critical mechanism underlying FGF1 ameliorating diabetes‐associated complications." (PMID 33788387, 2021). "FGF1-associated glucose level reduction and amelioration of cellular stress are potential protective effects of FGF1 against diabetes-induced liver injury." (PMID 32194395, 2020). "In the present study, FGF1 treatment caused significant increases in expression levels of Nrf2 in db/db mice, which ameliorated diabetes-induced oxidative stress in liver tissue." (PMID 32194395, 2020). "Our current study had demonstrated that FGF1 treatment blocked diabetes‐associated α‐SMA overexpression and collagen accumulation." (PMID 30320493, 2018). "In summary, in this study we successfully engineered FGF1 variants that effectively uncouple potent glucose-lowering effects from undesired mitogenic activity, addressing a critical hurdle for its therapeutic application in diabetes." (PMID 41520078, 2026). "Ongoing efforts to bridge the gap between diverse cellular responses to FGF1 and the associated normalization of glycemia may ultimately uncover novel strategies for achieving sustained diabetes remission." (PMID 32895383, 2020). "A variant of FGF1, devoid of mitogenic activity, improves glucose metabolism and insulin sensitivity in a rodent model, demonstrating a potential utility of FGF1 in treating diabetes in humans." (PMID 26594197, 2015). "Furthermore, we demonstrated that FGF1 treatment blocked diabetes-associated collagen accumulation." (PMID 32194395, 2020). "•Icv FGF1-induced diabetes remission drives in dorsal AgRP neurons a transcriptional state consistent with reduced activity." (PMID 41371441, 2026). "A role for arcuate nucleus neurons in FGF1-induced diabetes remission was strengthened further by evidence that functional melanocortin 4 receptor (MC4R)-signaling is required for this effect." (PMID 41371441, 2026). "Here, we used single-nucleus and spatial transcriptomics to characterize hypothalamic responses to FGF1 in Lepob/ob mice, identifying molecular and cellular changes that offer a feasible and novel explanation for sustained diabetes remission." (PMID 41371441, 2026). "Delineating the mechanisms by which a single icv injection of FGF1 leads to sustained diabetes remission in rodent models of T2D has implications for both basic and translational neuroendocrinology." (PMID 41371441, 2026). "For instance, FGF1 improves glucose homeostasis and lipid metabolism, making it a promising therapeutic candidate for diabetes and obesity." (PMID 40585885, 2025). "In these mice, we reported in 2016 that a single intracerebroventricular (icv) injection of fibroblast growth factor 1 (FGF1) can induce diabetes remission lasting months." (PMID 40371641, 2025). "A single intracerebroventricular injection of fibroblast growth factor 1 (FGF1) induces sustained remission of diabetes in ZDF rats and increases ARC PNN density, normalizing toward healthy levels." (PMID 40728680, 2025).
diabetes (continued). "FGF1 functions as a key metabolic regulator that governs glucose homeostasis and insulin sensitivity, and has shown therapeutic potential for type 2 diabetes mellitus." (PMID 41430037, 2025). "FGF1 has been shown to mitigate diabetes-induced hepatic steatosis, fibrosis, and apoptosis, playing a crucial role in hepatic glucose and lipid homeostasis." (PMID 40585885, 2025). "FGF-1 has also been found to alleviate diabetes-induced mouse germ cell death by decreasing ER stress and apoptotic cell death." (PMID 38542166, 2024). "It has been demonstrated that FGF1 partially ameliorates diabetes-induced beta cell dysfunction by improving insulin secretion at the pancreatic islet level." (PMID 37284218, 2023). "A single intracerebroventricular injection of FGF1 induced sustained diabetes remission for 18 weeks in mouse models of type 2 diabetes." (PMID 37284218, 2023). "Fibroblast growth factor 1 (FGF1) has emerged as a promising diabetes treatment, but its pharmaceutical role and mechanism against glucolipotoxicity-induced β-cell dysfunction remain uncharacterized." (PMID 36225175, 2022). "Remarkably, subcutaneously injection of FGF1 protein can significantly improve the insulin sensitivity and reduce the serum glucose levels in two mouse models of diabetes (ob/ob, db/db and diet-induced obese insulin resistant mice)." (PMID 35011683, 2021). "A higher FGF-1 concentration was more effective than a lower FGF-1 concentration in protecting against diabetes-induced inflammation." (PMID 34281287, 2021). "Previous study has demonstrated that FGF1 significantly ameliorates diabetes‐mediated liver damage (DMLD)." (PMID 33788387, 2021). "We found that diabetes significantly increases pro‐inflammatory factor levels (IL‐6 and IL‐1β), and FGF1 treatment remarkably reversed them." (PMID 33788387, 2021). "FGF1 can effectively prevent diabetes‐induced elevated apoptosis and inflammation, and consequently ameliorate liver injury though reducing RAGE expression and inhibiting the RAGE/NF‐κBp65 pathway." (PMID 33788387, 2021). "The expression levels of ICAM-1 and IL-1β were lower in the FGF-1 treatment group than in the diabetes group (p < 0.05)." (PMID 34281287, 2021). "FGF1 treatment reduces apoptosis and inflammation in the liver, and consequently ameliorates diabetes‐induced liver injury though suppressing RAGE pathway." (PMID 33788387, 2021). "Except for controlling the blood glucose, FGF1 also ameliorates many diabetes‐induced complications through multiple signalling pathways." (PMID 33788387, 2021). "FGF1 was regarded as a potential weapon for treating diabetes because of its excellent blood glucose control and insulin sensitization effects." (PMID 33788387, 2021). "We confirmed that FGF1 treatment not only significantly ameliorates diabetes‐induced elevated apoptosis in the liver, but also attenuates diabetes‐induced inflammation, then contributes to ameliorate liver dysfunction." (PMID 33788387, 2021). "Diabetes activates NF‐κBp65 activity in a variety of cell types, and FGF1 treatment reverses this effect and reduces inflammation." (PMID 33788387, 2021). "The findings indicate that FGF-1 treatment reduced the diabetes-induced expression of 8-OHdG, nitrotyrosine, and acrolein in rat retinas by reducing oxidative stress." (PMID 34281287, 2021). "All these changes in db/db mice were reversed by FGF1 treatment, suggesting that FGF1 inhibited diabetes-induced liver fibrosis by abolishing collagen accumulation in the liver." (PMID 32194395, 2020). "Consistent with western blotting results, FGF1 treatment significantly reversed diabetes-induced upregulation of the fluorescence intensity of p-PERK in the CA1 of hippocampus." (PMID 32460803, 2020). "Taken together, our results suggest that db/db mice had fatty livers, and FGF1 treatment reduced blood glucose and attenuated diabetes-induced hepatic steatosis." (PMID 32194395, 2020).
diabetes (continued). "To measure FGF1 treatment mediated inhibition of diabetes-induced ER stress in liver, we measured expression levels of ER stress protein markers." (PMID 32194395, 2020). "Taken together, these observations suggest that FGF1 ameliorated diabetes-induced hepatic apoptosis in db/db mice." (PMID 32194395, 2020). "Taken together, FGF1 administration effectively alleviates diabetes-induced Aβ1–42 deposition and synaptic dysfunction." (PMID 32460803, 2020). "FGF1 significantly reduced blood glucose and ameliorated diabetes-induced liver steatosis, fibrosis, and apoptosis." (PMID 32194395, 2020). "Previous studies reported that FGF1 inhibited oxidative stress and consequently blocked diabetes-induced cardiomyopathy." (PMID 32194395, 2020). "Taken together, these data suggest that FGF1 treatment markedly reversed diabetes-induced hepatic oxidative stress by regulating FGFR1-AMPK pathway." (PMID 32194395, 2020). "Taken together, these studies have suggested that FGF1 treatment effectively ameliorates diabetes-induced inferior spatial learning and memory function of mice." (PMID 32460803, 2020). "We confirmed that inhibition of cellular stress and restoring autophagy are the potential molecular mechanisms of FGF1 inhibition of diabetes-induced liver injury." (PMID 32194395, 2020). "One limitation is that we did not record food intake; this will be measured in a future study to fully understand the role of FGF1 in reducing glucose effect and ameliorating diabetes-induced liver injury." (PMID 32194395, 2020). "Mechanistic investigations showed that diabetes markedly induced oxidative stress and endoplasmic reticulum stress and that FGF1 treatment significantly attenuated these effects." (PMID 32194395, 2020). "Fibroblast growth factor 1 (FGF1) was first identified in brain and pituitary tissues, and functions as an insulin sensitizer in type 2 diabetes mellitus along with maintaining adipose tissue and metabolic homeostasis." (PMID 32615540, 2020). "A single peripheral injection of FGF1 in diabetic rodents normalizes diabetes within hours, while multiple doses promote insulin sensitization in as short as 3 weeks." (PMID 32372975, 2020). "Taken together, these data suggest that FGF1 treatment markedly reversed diabetes-induced hepatic oxidative stress in db/db mice." (PMID 32194395, 2020). "Taken together, these data suggest that FGF1 exerted effects on diabetes-induced liver injury by suppressing diabetes-induced ER stress." (PMID 32194395, 2020). "To date, the precise mechanisms and potential treating strategies of FGF1 for diabetes-induced cognitive decline (DICD) hasn’t been fully elucidated." (PMID 32460803, 2020). "To determine the mechanisms by which FGF1 protects against diabetes-induced liver damage, we examined apoptosis pathways." (PMID 32194395, 2020). "Taken together, these data suggest that FGF1 treatment significantly suppressed diabetes-induced ER stress." (PMID 32194395, 2020). "It was observed that diabetes had significantly decreased FGF1 expression and enhanced FGFR1 expression in hippocampus when compared with those in db/m mice." (PMID 32460803, 2020). "FGF1 effectively blocks diabetes-induced neuronal apoptosis and BDNF reduction, consequently ameliorates DICD though inhibiting PERK signaling and promoting PI3K/AKT signaling." (PMID 32460803, 2020). "Central icv injection of fibroblast growth factor 1 (FGF1) induces diabetes remission in animal models of T2DM in a process mediated by tanycyte activation that enhances insulin-independent glucose clearance." (PMID 31072002, 2019). "Here, we found that FGF1 administration significantly suppressed diabetes‐induced overexpression of NOX2 in kidney." (PMID 30320493, 2018). "Here, we have further confirmed that FGF1 significantly ameliorated the diabetes‐induced renal interstitial fibrosis and glomerular damage." (PMID 30320493, 2018).